SEMA4D (semaphorin 4D)
Diseases named in the same sentence as SEMA4D in open-access papers (continued):
Sharing a sentence is not in itself a finding about the gene and the disease.
vasculitis (3 papers, 2020 to 2024). "In the future, we need further mechanism researches to evaluate the exact role of Sema4D in KD vasculitis." (PMID 33381571, 2020). "Notably, our previous study demonstrated a positive correlation between Sema4D and CRP levels and Z-score in KD, suggesting that molecules from the Sema family may serve as progression markers in the development of KD vasculitis." (PMID 38678170, 2024).
autoimmune disease (2 papers, 2020 to 2023). A disorder resulting from loss of function or tissue destruction of an organ or multiple organs, arising from humoral or cellular immune responses of the individual to their own tissue constituents. "Although extensive studies have addressed the physiological and pathological effects of Sema4D on many autoimmune diseases, the potential role of Sema4D in immunoregulation and bone remodeling in AS pathogenesis has not yet been reported." (PMID 33013906, 2020).
breast tumor (2 papers, 2021 to 2025). "At odds with these findings, Sema4D and PlexinB1 levels detectable in human breast tumor samples appear of unclear prognostic significance." (PMID 33537086, 2021). "For instance, other known ligands of PLXNB2, such as SEMA5A and SEMA4D, are either not expressed or not detectable in breast tumors at the primary site." (PMID 40818975, 2025).
Cirrhosis (2 papers, 2021 to 2022). A chronic disorder of the liver in which liver tissue becomes scarred and is partially replaced by regenerative nodules and fibrotic tissue resulting in loss of liver function. "By contrast, in NAFLD livers, SEMA4D expression was detected in hepatocytes and lymphocytes as well in endothelial cells, and the expression was markedly higher in patients with advanced fibrosis/cirrhosis." (PMID 36551769, 2022).
endometrial carcinoma (2 papers, 2020 to 2023). A malignant tumor arising from the epithelium that lines the cavity of the uterine body. "In keeping with these findings, we evidence that SEMA4D is also found by our analysis in Uterine Corpus Endometrial Carcinoma (UCEC), in this case regulated by Paired box gene 8 (PAX8) which is a driver of uterine neoplasms and, again, associates with fibrosis." (PMID 33266472, 2020).
fibrosis (2 papers, 2018 to 2022). the formation of excess fibrous connective tissue in an organ or tissue in a reparative or reactive process. "To investigate the direct role of Sema4D in collagen production, we carried out an in vitro fibrosis assay." (PMID 29541402, 2018).
glioblastoma (2 papers, 2020 to 2024). The most malignant astrocytic tumor (WHO grade IV). "Pericytes mediate neo-angiogenesis in the glioblastoma mass, contacting both tumoral perivascular cells and brain endothelium through Semaphorin-4D (SEMA4D) and focal adhesion kinase (FAK)." (PMID 39513861, 2024).
glomerulonephritis (2 papers, 2013 to 2025). A renal disorder characterized by damage in the glomeruli. "In addition, Sema4D deficiency reduces kidney injury in glomerulonephritis models, likely by dampening immune responses through its receptors." (PMID 40507881, 2025).
head and neck carcinoma (2 papers, 2007 to 2022). A carcinoma that arises from the head and neck region. "Furthermore, it was shown that inhibiting the expression of Sema4D in human head and neck carcinoma cells leads to reduction of tumour burden and vascularity in a mouse xenograft model." (PMID 17519029, 2007).
liver cirrhosis (2 papers, 2021 to 2025). "Elevated levels of Sema4D have been observed in patients with liver cirrhosis and are positively correlated with liver and gallbladder damage, suggesting a role in inflammation-associated hepatic injury." (PMID 41321447, 2025).
lupus (2 papers, 2022 to 2025). "Similarly, markedly elevated serum SEMA4D levels have been demonstrated in patients with AAV, depicting a positive association with the BVAS score, and they were higher than in other autoimmune diseases, such as rheumatoid arthritis or systemic lupus erythematosus (SLE)." (PMID 40804869, 2025).
lupus nephritis (2 papers, 2015 to 2022). Glomerulonephritis in the context of systemic lupus erythematosus. "In a previous study of ours, we assessed the possible involvement of sema3A, sema4A and sema4D in contributing to or regulating glomerular inflammation in lupus nephritis." (PMID 25978359, 2015). "Both TrMacs and MoMacs showed increased expression of SEMA4D (CD100) in lupus nephritis." (PMID 36345939, 2022). "MoMacs in lupus nephritis biopsies showed increased expression of CCR5 and FRP3 in lupus nephritis, mirroring our findings in MRL-Lpr kidneys, and there was also increased expression of SEMA4D in both MoMac and TrMac subsets." (PMID 36345939, 2022).
lymphoma (2 papers, 2023 to 2026). A malignant (clonal) proliferation of B- lymphocytes or T- lymphocytes which involves the lymph nodes, bone marrow and/or extranodal sites. "Lymphoma patients have significantly higher levels of circulating pro- and anti-inflammatory cytokines IL-10, IL-6, and Sema4D as compared to healthy donors." (PMID 42194097, 2026).
oral squamous cell carcinoma (2 papers, 2019). "The SEMA4D role in tumor-induced angiogenesis was demonstrated particularly for oral squamous cell carcinomas (OSCC)." (PMID 31205625, 2019). "They demonstrated that expression of SEMA4D, which was under the control of the HIF-family of transcription factors, cooperated with VEGF to promote tumor growth and vascularity in oral squamous cell carcinoma (OSCC)." (PMID 31105696, 2019).
Rett syndrome (2 papers, 2021 to 2022). A severe neurodevelopmental disorder affecting the central nervous system. "This study expands mechanistic insight into Rett syndrome pathology and suggests the potential of anti-SEMA4D antibody therapy in this paediatric neurological disorder." (PMID 34502373, 2021). "The pre-clinical trial results suggest that anti-SEMA4D immunotherapy is a potentially promising therapeutic strategy to improve phenotype, coordination, cognition, locomotion, and respiration in Rett syndrome." (PMID 34502373, 2021). "Both the 4-week cohort (pre-symptomatic) and 8-week (symptomatic) anti-SEMA4D antibody-treated Rett syndrome cohorts showed significant improvements in the phenotypic clinical scores relative to the isotype control antibody groups." (PMID 34502373, 2021). "Here, we have demonstrated the therapeutic efficacy of anti-SEMA4D antibody treatment in alleviating phenotypic symptoms and functional deficits in a transgenic mouse model of Rett syndrome." (PMID 34502373, 2021). "We show that anti-SEMA4D antibody therapy not only prevents, but reverses, many Rett syndrome-specific phenotypes, including coordination, cognition, locomotion, and respiratory deficits in both pre-symptomatic and symptomatic mice." (PMID 34502373, 2021). "Therefore, anti-SEMA4D therapy remains a potential treatment for individuals diagnosed with Rett syndrome until such time that early intervention strategies such as pre-natal testing or early genetic testing are implemented in healthcare systems." (PMID 34502373, 2021). "Here, we demonstrate reversal of key features of the Rett syndrome phenotype following antibody blockade of SEMA4D as well as upregulation of SEMA4D expression during disease progression and the effects of SEMA4D on reactive transformation of mutant glial cells expressing the Plexin B1 receptor." (PMID 34502373, 2021). "In this study, we demonstrated that anti-SEMA4D immunotherapy not only reverses Rett-like symptoms but also prevents them, however, the prevention of Rett syndrome neurological signs and symptoms remains challenging as diagnosis is mostly achieved after these neurological symptoms are evident." (PMID 34502373, 2021). "The rapid response to the anti-SEMA4D antibody therapy in the symptomatic mice suggests anti-SEMA4D immunotherapy may have potential to treat the Rett syndrome girls who are usually diagnosed after symptom onset." (PMID 34502373, 2021). "Thus, SEMA4D is a unique target of therapeutic development for multiple pathological conditions including Rett syndrome where glial activation is believed to be involved in the pathogenesis of disease." (PMID 34502373, 2021). "Blocking SEMA4D-induced gliosis may preserve normal glial and neuronal function and rescue neurological dysfunction in Rett syndrome." (PMID 34502373, 2021).
sarcoma (2 papers, 2012 to 2023). A usually aggressive malignant neoplasm of the soft tissue or bone. "Similarly, recent work has revealed a correlation between high levels of SEMA4D expression in some sarcomas and poor overall patient prognosis." (PMID 23202951, 2012).
Stroke (2 papers, 2020 to 2022). Sudden impairment of blood flow to a part of the brain due to occlusion or rupture of an artery to the brain. "Sema4D and Sema7A signaling mainly participates in inflammatory response in pericytes and microglial cells after stroke." (PMID 35350431, 2022). "Mechanistically, Sema4D/PlexinB1 signaling promotes an inflammatory response in pericytes and microglial cells and increases BBB permeability via regulating pericytes function after stroke." (PMID 35350431, 2022).
acute leukemia (1 paper, 2022). A clonal (malignant) hematopoietic disorder with an acute onset, affecting the bone marrow and the peripheral blood. "However, it remains unknown whether Sema4D is associated with the clinical characteristics of acute leukemia." (PMID 35401878, 2022). "We have previously shown that Sema4D is highly expressed in acute leukemia, and the soluble Sema4D level is increased in plasma." (PMID 35401878, 2022). "In this study, to further elucidate the role of Sema4D as a biomarker in acute leukemia, we correlated its expression in acute leukemia and the level of its soluble Sema4D in serum with clinical characteristics." (PMID 35401878, 2022). "We have previously shown that, in acute leukemia, Sema4D is highly expressed and soluble Sema4D levels in plasma are also elevated." (PMID 35401878, 2022). "Our study with overexpression and knockdown of Sema4D in acute leukemia cell lines showed that Sema4D promotes proliferation and inhibits apoptosis in acute leukemia by activating the PI3K/AKT and ERK signaling pathways." (PMID 35401878, 2022). "In acute leukemia, soluble Sema4D level in serum is positively correlated with Sema4D expression in PBMCs, leukocyte number, and peripheral blast number." (PMID 35401878, 2022). "Acute leukemia development may be monitored by ELISA detection of soluble Sema4D, which is easier and more convenient than traditional methods." (PMID 35401878, 2022). "The function of soluble Sema4D in acute leukemia will be investigated in a future study." (PMID 35401878, 2022). "To explore whether Sema4D is a clinically potential biomarker in acute leukemia, we investigated the correlation of Sema4D expression in PBMCs and BMMCs with clinical characteristics in this study." (PMID 35401878, 2022). "A high level of soluble Sema4D is also present in the plasma of acute leukemia patients." (PMID 35401878, 2022). "We previously found that Sema4D is highly expressed in pediatric acute leukemia, which is a serious threat to children and one of the main causes of death in children; Sema4D expression is also correlated with the phosphorylation of PI3K, ERK, and AKT in PBMCs of acute leukemia patients." (PMID 35401878, 2022). "Sema4D level is not correlated with risk classification and early remission status, suggesting it may not be the main drive force in acute leukemia development and is not involved in the relapse." (PMID 35401878, 2022). "The soluble Sema4D level in serum is positively correlated with Sema4D expression in PBMCs, leukocyte number, and peripheral blast number, suggesting that soluble Sema4D may be regarded as a potential biomarker for pediatric acute leukemia development and prognosis." (PMID 35401878, 2022). "In acute leukemia, Sema4D expression in BMMCs was not correlated with Sema4D expression in PBMCs." (PMID 35401878, 2022).
allergic disease (1 paper, 2022). An immune response that occurs following re-exposure to an innocuous antigen, and that requires the presence of existing antibodies against that antigen. "This could be related, at least in part, to a suppressive effect of Sema4D on Treg cells which are well-known for their downregulatory effects on Th2 effector cells and for controlling allergic diseases." (PMID 35328445, 2022).
ankylosing spondylitis (1 paper, 2020). An autoimmune chronic inflammatory disorder characterized by inflammation in the vertebral joints of the spine and sacroiliac joints. "We undertook this study to investigate the mechanism by which Sema4D affects the pathogenic progress of ankylosing spondylitis (AS)." (PMID 33013906, 2020).
Autoimmunity (1 paper, 2020). The occurrence of an immune reaction against the organism's own cells or tissues. "In addition, several studies have shown that Sema4D is involved in the pathogenesis of autoimmunity." (PMID 33013906, 2020).
bladder urothelial carcinoma (1 paper, 2023). "The results showed that SEMA4D expression was negatively correlated with TMB in most tumors, including DLBC, KIRC, LGG, LIHC, LUSC, THCA, and THYM, but was positively correlated with TMB in bladder urothelial carcinoma (BLCA), BRCA, and uterine corpus endometrial carcinoma (UCEC)." (PMID 37287907, 2023).
bone metastasis (1 paper, 2018). Transfer of a neoplasm from its primary site to bones. "Because of the potential role of Sema4D in bone metastasis, this molecule should be further explored in these specific disease groups, and bone metastases should be included in clinical endpoints." (PMID 29971044, 2018).
chronic kidney disease (1 paper, 2025). Impairment of the renal function secondary to chronic kidney damage persisting for three or more months. "Sema4D is a marker applicable to multiple high-risk populations (such as heart failure, chronic kidney disease (CKD), atherosclerosis, and diabetes)." (PMID 41536360, 2025).
generalized tonic-clonic seizures (1 paper, 2024). "The importance of promoting the membrane localization of Sema4D is emphasized by the identification of a human mutation in Sema4D, Q497P associated with tonic-clonic seizures." (PMID 39152101, 2024). "Over the course of this study, we identified a patient presenting with generalized tonic-clonic seizures that has a de novo mutation in SEMA4D (see case report in supplemental note 1)." (PMID 39152101, 2024). "The importance of the membrane localization of Sema4D for its biological function is highlighted by the SEMA4D-497P mutation described here in a patient with generalized tonic-clonic seizures." (PMID 39152101, 2024).
hyperphosphatemia (1 paper, 2025). Abnormally high level of phosphate in the blood. "In the context of CKD, where hyperphosphatemia is a key driver of pathological vascular calcification, targeting Sema4D may offer particular clinical benefit." (PMID 40507881, 2025).
hypogonadism (1 paper, 2011). A disorder characterized by decreased function of the gonads. "Although no hypogonadism was detected in Sema4D −/− mice, they presented a decreased fertility." (PMID 22046317, 2011).
mesothelioma (1 paper, 2023). A usually malignant and aggressive neoplasm of the mesothelium which is often associated with exposure to asbestos. "SEMA4D expression was negatively correlated with MSI in most tumors, including LIHC, mesothelioma (MESO), PAAD, rectum adenocarcinoma (READ), SKCM, TGCT, and UCS, but was positively correlated with MSI in BRCA, CESC, LUAD, and UCEC." (PMID 37287907, 2023).
oral cancer (1 paper, 2023). "SEMA4D is expressed at high levels on MOC1 oral cancer cells." (PMID 37287907, 2023). "Blocking MOC1 oral cancer cells SEMA4D does not directly affect tumor cell proliferation but reduces the production of chemokines by tumor cells, resulting in reduced MDSC and enhanced T lymphocyte response." (PMID 37287907, 2023).
oral lichen planus (1 paper, 2023). Oral lichen planus is a chronic inflammatory oral condition of unknown aetiology characterized by T-cell-mediated chronic immune response and abnormal epithelial keratinization cycle. "Moreover, a published study has uncovered that Sema4D elicits oral lichen planus CD8+ T-cell migration by binding to PlexinB1 via AKT/NF-KB cascade." (PMID 37901456, 2023).
osteoarthritis (1 paper, 2018). A noninflammatory degenerative joint disease occurring chiefly in older persons, characterized by degeneration of the articular cartilage, hypertrophy of bone at the margins and changes in the synovial membrane. "Segmental copy number loss in the region of the Sema4D gene was seen in one third of patients with acetabular dysplasia, which increases risk of osteoarthritis, but a causal relationship was not explored." (PMID 29971044, 2018).
Osteopenia (1 paper, 2016). Osteopenia is a term to define bone density that is not normal but also not as low as osteoporosis. "One obvious consequence of this discovery is the value of Sema4D inhibition in the arrest of osteopenia." (PMID 26910109, 2016).
periapical periodontitis (1 paper, 2022). Inflammation of the periapical tissue. "It was also reported that Enterococcus faecalis, one of the major pathogens implicated in periapical periodontitis, promotes periapical bone resorption via increasing Sema4D expression." (PMID 35628440, 2022).
periodontitis (1 paper, 2022). An acute or chronic inflammatory process that affects the tissues that surround and support the teeth. "The present study examined the functional role of Sema4D in osteoclastogenesis induced in a mouse model of ligature-induced periodontitis." (PMID 35628440, 2022). "Future studies are needed to address the nature of receptors for soluble Sema4D expressed in periodontitis." (PMID 35628440, 2022). "Nonetheless, the possible role of Sema4D produced in periodontitis lesions, which is perhaps produced in a soluble form, remains elusive." (PMID 35628440, 2022). "In short, the pathophysiological role of Sema4D in periodontitis requires further study." (PMID 35628440, 2022). "However, we have employed the mouse model of ligature-induced periodontitis to determine the possible role of Sema4D in alveolar bone regeneration in PD." (PMID 35628440, 2022). "While anti-Sema4D-mAb downmodulated the bone-resorption induced in mouse periodontitis, it neither affected local production of TNF-α and RANKL nor systemic skeletal bone remodeling." (PMID 35628440, 2022). "According to the histology section stained with H&E, the inflammatory infiltrates increased in the ligature-induced periodontitis lesion irrespective of the administration with anti-Sema4D mAb." (PMID 35628440, 2022). "Additionally, our group recently discovered that Sema4D expressed on osteoclasts is cleaved by tumor necrosis factor-alpha converting enzyme (TACE; also called ADAM17) (paper under review), which plays a relevant proinflammatory role in periodontitis." (PMID 35628440, 2022).
schistosomiasis (1 paper, 2020). An infectious disease caused by parasitic trematodes of the genus Schistosoma that colonize human blood vessels and release eggs that can cause granulomatous reactions leading to acute (swimmer's itch or acute schistosomiasis syndrome) or chronic disease. "In addition, we found Sema4D in serum of schistosomiasis japonicum patients were increased than healthy controls." (PMID 32944173, 2020).